STAT3 (signal transducer and activator of transcription 3)
Diseases named in the same sentence as STAT3 in open-access papers (continued):
Sharing a sentence is not in itself a finding about the gene and the disease.
glioma (continued). "In glioma cell line U87 treated with 30 μm EGCG, it was observed that EGCG effectively reduced WT-MT1-MMP-mediated Src and STAT3 phosphorylation, upregulated glioma cell apoptosis and inhibited neurosphere formation in glioma cells." (PMID 36923251, 2023). "Various molecular pathways are involved in the radioresistance of gliomas; on top of them, there are AKT, Wnt/β-catenin, and STAT3." (PMID 37821870, 2023). "Our study found that ARSD can promote glioma development by regulating immune microenvironment and JAK2/STAT3 signaling pathway, which provided a potential therapy target for glioma treatment." (PMID 37766864, 2023). "Under the hypoxia condition, STAT3 nuclear translocation leads to the overexpression of VEGF and enhances the endothelial tube formation in gliomas." (PMID 38201528, 2023). "Aberrant activation of STAT3 has been found in GBM, and correlates with mesenchymal differentiation and poor prognosis in human gliomas." (PMID 37298405, 2023). "In gliomas, inactivation of ZDHHC15 blocked glioma cells proliferation by decreasing activation of Signal Transducer and Activator of Transcription 3 (STAT3) and knockdown of ZDHHC12 reduced the growth, migration, and invasion capabilities of glioma cells." (PMID 37759431, 2023). "STAT3 is then activated by phosphorylation and represses transcription of the IL8 gene, which ultimately suppresses glioma cell proliferation and invasiveness." (PMID 36557902, 2022). "As a key molecule, activation of STAT3 promote proliferation, migration, and epithelial-mesenchymal transition (EMT) of glioma cells." (PMID 34992215, 2022). "The expression of IL-6 often remains at a high level in gliomas, especially GBM, which results in the overactivation of the JAK2/STAT3 pathway and induces stronger EMT." (PMID 36338770, 2022). "This study found that the high expression of LINC00346 is linked to the high expression of STAT3 and CD204, and LINC00346 may serve as a positive function in the STAT3 expression, enabling macrophages to differentiate into M2 and supporting the progression of gliomas." (PMID 36311792, 2022). "Further investigations revealed that TMEM158 enhanced glioma cell proliferation, migration, and invasion as well as the progression of epithelial mesenchymal transition (EMT) by activating STAT3 signaling in vitro as well as in a mouse model." (PMID 36425564, 2022). "The overexpression of EGFR will excessively activate EGFR-dependent signal pathways including PI3K/Akt, JAK2/STAT3, and Ras/MAPK in the course of EMT in gliomas." (PMID 36338770, 2022). "Immunohistochemical staining revealed that five genes (ZEB1, CA9, HSPb1, STAT3, and TNFAIP3) had a higher expression in glioma tissues than in normal tissues." (PMID 35711838, 2022). "Finally, we asked if the E2F/STAT3 inhibitor combination may find its utility in glioma treatment." (PMID 35058574, 2022). "In glioma, GOLPH3 was found to facilitates the interaction of JAK2 and STAT3, leading to activation of the STAT3 pathway." (PMID 35372504, 2022). "We analyzed SOX9, STAT3/p-STAT3, and PML expression in a set of established glioma cell lines and patient-derived cells cultures by immunoblot." (PMID 35562901, 2022). "It was observed that NS formation is accompanied by the activation of five common gliomas of TFs, SOX2, UBTF, NFE2L2, TCF3 and STAT3." (PMID 36231068, 2022). "PD-L1 is regulated by various molecules, such as STAT3 in T-cell lymphoma and melanoma, STAT and AP-1 in classical Hodgkin lymphoma, the ZEB1 axis in non-small-cell lung cancer, PI3K in glioma, and Myc in multiple tumors." (PMID 36249036, 2022). "STAT3 siRNA-loaded SPNPs showed efficient penetration of the BBB, significant downregulation of the STAT3 expression and tumor regression in both GL26 glioma cell and GL26 syngeneic mouse models." (PMID 36153528, 2022).
glioma (continued). "In this study, LINC00346 expression in gliomas was determined by FISH, and type 2 macrophage surface marker CD204 and its key transcription factor STAT3 were determined by IHC staining." (PMID 36311792, 2022). "Activation of STAT3 and inhibition of the NF-κB pathway which foster an immunosuppressive TME also promote the proliferation, migration and invasion of glioma cells in vitro as well as in vivo." (PMID 36555253, 2022). "In turn, EGFR triggers the activation of signalling cascades impinging on signal transducer and activator of transcription 3 (STAT3), AKT, and the mitogen-activated protein kinases (MAPKS) ERK1/2, thereby promoting the oncogenic phenotype of glioma cells." (PMID 35269953, 2022). "In this study, we found that ciglitazone decreased phosphor-STAT3 (Try 705) activities, coupled with the reciprocal increase of SHP-2 in both glioma cell line and glioma tissue." (PMID 36362294, 2022). "We treated MOG-G-UVW, U-251, and SF-188 (EV and ATRX KO) high-grade glioma cell lines with different concentrations (5 μM and 10 μM) of BTK, STAT3, and RTK inhibitors for 48 h in order to assess cell viability." (PMID 35406561, 2022). "In glioma, CRNDE was upregulated and promote tumor progression via attenuating miR-384/PIWIL4/STAT3 axis, it also contributed to temozolomide (TMZ) resistance by autophagy, knockdown of CRDNE enhanced TMZ chemosensitivity." (PMID 36281290, 2022). "In order to determine if ferroptosis is affected by PF treatment, we examined the expressions of STAT3/p-STAT3, Nrf2, and GPX4 in PF-treated glioma U87 cells, and found out that all these factors are inhibited at the protein level in a dosage-dependent manner." (PMID 36618071, 2022). "CRNDE has been reported to promote the proliferation, migration, and invasion of glioma through attenuating miR-384/PIWIL4/STAT3 axis and facilitating EGFR activation to modulate glioma growth." (PMID 36033510, 2022). "Distinct proteins have been identified in different glioma subtypes, including YKL40, fibronectin 1 (FN1), EGFR, and Stat3." (PMID 35436989, 2022). "CD68+p-STAT3+ (P = 0.0306) and CD163+p-STAT3+ (P = 0.0165) cells were significantly enriched in regions of necrosis in gliomas and brain metastases, respectively." (PMID 35316217, 2022). "Recently, we showed that DC–T cell cluster events are promoted in the glioma TME by combined radiation and p-STAT3 inhibitor (WP1066) treatments that confer long-term survival to animals with intracranial tumors." (PMID 35316217, 2022). "Mechanistically, we further confirmed that TMEM158 enhanced glioma cells proliferation, migration, and invasion as well as the progression of EMT by activating STAT3 signaling." (PMID 34992215, 2022). "Among these seven validated hits, we further characterized the inhibitors targeting BTK (ibrutinib), STAT3 (niclosamide), and RTK (pazopanib), as previous studies have indicated the potential of these drugs to treat high-grade glioma." (PMID 35406561, 2022). "Mechanistically, miR-3591-3p can directly target CBLB and MAPK1 in macrophages and glioma cells, respectively, and further activate the JAK2/PI3K/AKT/mTOR, JAK2/STAT3, and MAPK signaling pathways." (PMID 36085418, 2022). "In the microenvironment of glioma and in the tumor microenvironment, the EGFR and the IL6 signaling pathway play important roles in activating STAT3." (PMID 35783263, 2022). "In glioma, NIC promotes the overexpression of ALK4, which significantly downregulates the phosphorylation of JAK 2 and STAT3, thus inhibiting the migration and invasion ability of glioma cells." (PMID 36555754, 2022). "In our study, we found that anticarin β inhibits clonal spheres forming in human glioma cells and reduces the expression of stemness-related markers, such as Nanog, Oct4, Sox2, CD133, STAT3, and CD44." (PMID 34408983, 2021). "To determine the mechanism by which STAT3 was inhibited by the combination of sorafenib and TMZ, we assessed JAK2, an upstream molecule that regulates STAT3 in glioma cells." (PMID 34277607, 2021).
glioma (continued). "In vitro experiments reveal that ELK3 overexpression can increase the proliferation and migration of gliomas cells and play a role through the regulation of JAK2 the STAT3 signaling pathway." (PMID 34976781, 2021). "Taken together, in glioma, lncRNA CASC9 increases STAT3 expression by sponging miR‐519d, while STAT3 interacts with the CASC9 promoter to accelerate CASC9 expression." (PMID 34425834, 2021). "To further demonstrate how ELK3 regulates these pathways to affect the malignant progression of gliomas, we explored the regulation of JAK2/STAT3 by ELK3 through western blot experiments." (PMID 34976781, 2021). "The results showed that NC inhibited the glioma EMT process and the properties of glioma stem‐like cells by modulating the JAK2/STAT3 signaling pathway, suggesting the potential of NC to serve as an effective anti‐glioma drug." (PMID 33788424, 2021). "In conclusion, our study confirmed that sorafenib enhanced the temozolomide sensitivity of human glioma cells through oxidative stress and JAK2/STAT3 signaling pathway inhibition." (PMID 34277607, 2021). "The mechanism of TMZ resistance reported so far is related to the heterogeneity of glioma cells, upregulation of O6-methylguanine DNA methyltransferase (MGMT), DNA repair, and signal transducer and activator of transcription 3 (STAT3)." (PMID 33614649, 2021). "The co-inhibition of STAT3 and MET induce glioma tumor cells destruction by reactivating apoptosis mechanisms." (PMID 34440802, 2021). "STAT1, STAT3, STAT5A, STAT5B, and STAT6 mRNA expression levels were significantly upregulated in glioma (including GBM, astrocytoma, oligodendroglioma, and anaplastic astrocytoma), compared with normal brain tissues or neural stem cells." (PMID 34276757, 2021). "HOXB5 was overexpressed in glioma and transcriptionally regulated IL6 expression and promoted the proliferation of GSCs via JAK2/STAT3 signaling." (PMID 33858489, 2021). "In conclusion, our results demonstrate that NC effectively inhibits the EMT process and cancer stem cell‐like properties in glioma cells and these effects of NC were achieved via JAK2/STAT3 signaling." (PMID 33788424, 2021). "Compared to WHO grade II and grade III glioma, GBM had significantly higher expression of Nestin, STAT3, and CD133." (PMID 34638384, 2021). "Our analysis of clinical data from the TCGA database indicated that mTOR, STAT3, and CDK6 are collectively hyper-expressed in both low-grade glioma and GBM cohorts." (PMID 34572040, 2021). "The results indicate that sorafenib enhanced the temozolomide sensitivity of human glioma cells by inducing oxidative stress-mediated autophagy and JAK2/STAT3-AIF axis." (PMID 34277607, 2021). "It exerts the sponge effect on miR-491-5p, thus upregulating LIF and activating the LIF/STAT3 axis for promoting proliferation and EMT in glioma." (PMID 34729101, 2021). "Collectively, our study confirmed that sorafenib enhanced the temozolomide sensitivity of human glioma cells through oxidative stress-mediated autophagy and JAK2/STAT3-AIF axis." (PMID 34277607, 2021). "It has been reported that STAT3 can be activated by Janus-activated kinases (JAKs) and c-Src, thus, we evaluated the expression levels of JAK2 and Src in glioma cells after incubation with β-elemene by western blot analysis." (PMID 34257541, 2021). "The subsequent activated LIF/STAT3 signaling was responsible for promoting proliferation and EMT in glioma." (PMID 34729101, 2021). "The EGFR and MET activation and the downstream of EGFR and MET signaling pathways, such as p-AKT, p-p38, p-STAT3 and p-p65 in TMZ-resistant glioma cells, were also mitigated by BIP-MPC-NP, as expected." (PMID 32001707, 2020). "The report from Chen indicated that PD-L1 modulated immune cell infiltration in glioma microenvironment (TME) and served as signaling protein control multiple pathways including STAT3, PI3K/AKT/mTOR, Ras/ERKsignaling pathways." (PMID 32061256, 2020).
glioma (continued). "After the inhibition of STAT3 is released, IL-6 activates the STAT3 signal cascade, which leads to an increase in the expression level of VEGF in glioma and contributes to tumor vessel formation." (PMID 33511267, 2020). "TrkB.T1 enhances PDGF-driven gliomas in vivo, augments PDGF-induced Akt and STAT3 signaling in vitro, while next generation sequencing broadly implicates TrkB.T1 in the PI3K signaling cascades in a ligand-independent fashion." (PMID 32532995, 2020). "Recently, reports had been published that several biomarkers such as MGMT, STAT3, and APNG were involved in the TMZ resistance of gliomas." (PMID 33362537, 2020). "The crosstalk signaling molecules of EGFR and MET pathways (p-AKT, p-p38, p-STAT3 and p-p65) were also mitigated by BIP-MPC-NP in TMZ-resistant glioma cells." (PMID 32001707, 2020). "We found that the knockdown of hnRNPA2/B1 in glioma cells strongly inhibited AKT and STAT3 phosphorylation." (PMID 32463472, 2020). "First, we analyzed the relationship between STAT3 mRNA and malignancy on the basis of World Health Organization (WHO) grade, GBM subtype, and GBM status using 1,837 samples from 4 glioma datasets." (PMID 32483429, 2020). "For example, in glioma, via the MYD88-TLR4 pathway, glioma stem cells stimulate the TAMs to produce IL-6, which, in turn, will stimulate the EMT via the JAK/STAT3/Snail pathway." (PMID 33228048, 2020). "Mechanistically, ACYP2 promoted malignant progression of glioma cells through regulating intracellular Ca2+ homeostasis via its interaction with PMCA4, thereby activating c-Myc and PTP1B/STAT3 signals." (PMID 32517717, 2020). "Compared with the shRNA control, knockdown of TRIM59 significantly inhibited p-STAT3, PIM1 mRNA expression, glioma sphere formation, and tumorigenicity of intracranial xenografts, but increased mH2A1 protein levels." (PMID 31488827, 2019). "Elevated STAT3 signaling has been attributed to the malignancy of GBM and the generation of glioma stem cells." (PMID 31269723, 2019). "Then, we knocked down ELTD1 with short hairpin RNAs in U-87MG and U-138MG glioma cells and found that the protein levels of p-JAK, p-STAT3, HIF-1α, and Frataxin notably decreased compared with the levels in the control group." (PMID 31554859, 2019). "Acetylation of STAT3 and NF-κB in SRT2183-treated glioma cells was examined using immunoprecipitation." (PMID 31319814, 2019). "In the present study, we found that STAT3 was activated upon EV71 infection in mouse primary astrocytes and human T98G glioma cells." (PMID 31575039, 2019). "Re-expression of shRNA-resistant TRIM59 WT or S308D mutant rescued p-STAT3, PIM1 mRNA expression, glioma sphere formation, and tumorigenesis of intracranial xenografts, but inhibited mH2A1 protein levels." (PMID 31488827, 2019). "Hypoxia was shown to induce STAT3 nuclear translocation, leading to upregulation of VEGF expression and enhanced endothelial tube formation in gliomas, indicating the potential of STAT3 targeting in reducing tumor neovascularization." (PMID 31698775, 2019). "Both erlotinib and Roscovitine treatments markedly inhibited TRIM59 nuclear translocation, p-STAT3, PIM1 mRNA expression, and glioma sphere formation, but increased mH2A1 protein levels, validating our observations in LN229/EGFR GBM cells." (PMID 31488827, 2019). "Vandetanib inhibits signaling pathways activated by EGFRvIII, such as STAT3, AKT, and Bcl-xL, thus reducing cell growth and angiogenesis in glioma cell lines that express EGFRvIII." (PMID 30486451, 2018). "This molecular mechanism between STAT3 and FOXP1 can serve as a therapeutic target for glioma treatment." (PMID 30134017, 2018). "This was the first time that the molecular mechanism between STAT3 and FOXP1 in glioma cells was discussed." (PMID 30134017, 2018). "STAT3 promoted cell proliferation, inhibited cell apoptosis and enhanced cell invasion through promoting FOXP1 transcription in glioma cells." (PMID 30134017, 2018).
glioma (continued). "Collectively, we conclude that nuclear-Smad6 enhances glioma development by inducing PIAS3 degradation and subsequent STAT3 activity upregulation." (PMID 29950561, 2018). "As far as STAT3 phosphorylation on Ser727, overexpression of CK2 has been shown to decrease it in C6 glioma cells through a mechanism involving CK2 activation of protein phosphatase PP2A." (PMID 29464030, 2018). "The complicated mechanisms of PIAS3 in tumorigenesis indicate that besides STAT3, other potential downstream pathways mediating the cancer-promotion of Smad6–PIAS3 axis in gliomas still need to be studied." (PMID 29950561, 2018). "Quantitative real‐time PCR (qRT‐PCR) and Western blot assay were administered to assess the mRNA and protein expression levels of STAT3 and FOXP1 in glioma tissues and cells, respectively." (PMID 30134017, 2018). "Some intriguing aspects of the core gene set identified in this study include the well-studied glioma-related genes ANGPT2, CD44, SPP1, STAT3, PDGRFA, and TOP2A (all up-regulated), and BRSK1, DKK3, FGFR2, MAPK9, MEF2C, and PTEN (all down-regulated)." (PMID 29352201, 2018). "A previous study has reported that p-STAT3 expression is inversely correlated to GRIM-19 expression in gliomas and that GRIM-19 negatively regulates STAT3 activity in glioma cells." (PMID 29074558, 2017). "STAT3 is a downstream effector of EGFR, activated in 60% of GBM patients, promotes progression in animal models of glioma, and negatively correlates with survival." (PMID 29129908, 2017). "In glioma stem-like cells, arsenic trioxide (ATO) inhibited the phosphorylation and activation of Akt and Stat3 through Notch signaling blockade." (PMID 28157712, 2017). "In fact, it was recently observed that the IGFBP2-neutralizing antibody leads to a reduction in the levels of phosphorylated EGFR, STAT3, and AKT in human glioma cells." (PMID 28036255, 2017). "Our analyses of clinical gliomas reveal a close correlation between co-expression of TRIM24/p-EGFR, TRIM24/H3K23ac and TRIM24/p-STAT3 with poor prognoses in GBM patients." (PMID 29129908, 2017). "Finally, we determined the HDAC3 protein, STAT3 phosphorylation and the core apoptosis protein Caspase 3 level in glioma cells treated with Coptis Chinensis using western blot to explore the effect of Coptis Chinensis intervention on the biological mechanisms in glioma cells." (PMID 29212474, 2017). "To establish the functional relevance of STAT3 as a downstream effector of ATM in maintaining the stemness of glioma stem cells, we transduced D456MG-ATM KO cells with a constitutively active STAT3 (STAT3C) or a dominant-negative STAT3 (STAT3DN)." (PMID 28337983, 2017). "Two genes contributing to the malignant progression of various cancer types notably gliomas WHO grade II–IV, IL6 and STAT3, were modulated by either molecules." (PMID 28467792, 2017). "Chang’s research also uncovered that miR-203 sensitizes glioma cells to radiation by modulating AKT and STAT3 pathways to repress DDR." (PMID 29246031, 2017). "In glioma cells, EZH2 binds to and methylates STAT3, leading to enhanced STAT3 activity by increased tyrosine phosphorylation of STAT3, especially in GSC." (PMID 29228694, 2017). "The newly established roles of TRIM24 and H3K23ac in tumorigenesis provide a strong rationale for targeting them to treat glioma patients with high EGFR and STAT3 signaling activity." (PMID 29129908, 2017). "We also compared the activated states of STAT3 among CD133+, CD133−, and their parental cells from C6 glioma cells and found that CD133+ exhibited the highest phosphorylated state." (PMID 29284440, 2017). "In this study, we found that Coptis Chinensis functioned similarly to VPA to down-regulate STAT3 phosphorylation level by reducing the expression of HDAC3, then affected the function and biological characteristics of glioma cells." (PMID 29212474, 2017).